KCNQ4 (potassium voltage-gated channel subfamily Q member 4)
Description:
Pore-forming subunit of the voltage-gated potassium (Kv) channel involved in the regulation of sensory cells excitability in the cochlea. KCNQ4/Kv7.4 channel is composed of 4 pore-forming subunits assembled as tetramers. Promotes the outflow of potassium ions in the repolarization phase of action potential which plays a role in regulating membrane potential of excitable cells. The channel conducts a slowly activating and deactivating current. Current often shows some inward rectification at positive potentials. Channel may be selectively permeable in vitro to other cations besides potassium, in decreasing order of affinity K(+) = Rb(+) > Cs(+) > Na(+). Important for normal physiological function of inner ear such as sensory perception of sound.
Synonyms: Kv7.4; DFNA2; DFNA2A
Tractability: Small molecule: an approved drug acts on it; a structure with a bound ligand is known; a high-quality ligand is known; it belongs to a druggable protein family. Antibody: its Gene Ontology location is reachable by antibodies, with high confidence; UniProt places it where antibodies can reach, with medium confidence; UniProt predicts a signal peptide or a membrane-spanning region. PROTAC: a small molecule that binds it is known.
Target class: Potassium channels; Ion channel; Voltage-gated ion channel; Voltage-gated potassium channel
Gene: Protein-coding gene on chromosome 1 (40,783,675 to 40,840,452, forward strand). Ensembl gene ENSG00000117013.
Subcellular location: Basal cell membrane
Pathways (Reactome):
Sensory Perception: Sensory processing of sound by inner hair cells of the cochlea; Sensory processing of sound by outer hair cells of the cochlea
Neuronal System: Voltage gated Potassium channels
Gene Ontology:
Molecular function: protein binding; voltage-gated potassium channel activity; potassium channel activity; monoatomic ion channel activity
Biological process: potassium ion transmembrane transport; potassium ion transport; sensory perception of sound; monoatomic ion transport; negative regulation of synaptic transmission, dopaminergic; transmembrane transport
Cellular component: basal plasma membrane; plasma membrane; voltage-gated potassium channel complex; membrane
Genetic constraint (gnomAD): Loss-of-function variants: 30 observed, 67.58 expected, observed/expected ratio (o/e) 0.44, 90% interval 0.33 to 0.6. The upper end of that interval is the gene's LOEUF score, 0.6, which puts it in group 2 of 6, group 1 being the genes least tolerant of losing a copy. Missense variants: 795 observed, 896.5 expected, observed/expected ratio (o/e) 0.89, 90% interval 0.84 to 0.94. Synonymous variants: 367 observed, 361.89 expected, observed/expected ratio (o/e) 1.01, 90% interval 0.93 to 1.11.
Gene-disease validity (ClinGen):
ClinGen rates the evidence that KCNQ4 causes each of these diseases.
nonsyndromic genetic hearing loss (autosomal dominant): Definitive.
Homologues: Orthologues: chimpanzee KCNQ4 (99% identical), macaque KCNQ4 (99% identical), dog KCNQ4 (98% identical), mouse Kcnq4 (97% identical), rat Kcnq4 (97% identical), pig KCNQ4 (96% identical), guinea pig KCNQ4 (94% identical), rabbit KCNQ4 (85% identical), tropical clawed frog kcnq4 (71% identical), zebrafish kcnq4 (16% identical). Paralogues in human: KCNQ5 (58% identical), KCNQ2 (52% identical), KCNQ3 (44% identical), KCNQ1 (35% identical), KCNB2 (18% identical), KCNA4 (14% identical), KCNA3 (14% identical), KCNA5 (14% identical), KCNF1 (13% identical), KCNA1 (13% identical), KCNA10 (13% identical), and 19 more.
Diseases named in the same sentence as KCNQ4 in open-access papers:
KCNQ4 is named in the same sentence as 61 diseases in open-access papers, as found by Europe PMC text mining. Sharing a sentence is not in itself a finding about the gene and the disease. The quoted sentences say what the papers report.
hearing loss (53 papers, 2011 to 2026). "Genetic analysis was conducted through next-generation sequencing (NGS) carried out using a panel of genes associated with hearing loss including the KCNQ4 gene." (PMID 40178561, 2025). "In humans, mutations in KCNQ4 cause nonsyndromic sensorineural hearing loss with an autosomal dominant inheritance pattern, and this hearing loss is aggravated after noise exposure." (PMID 38956136, 2024). "The KCNQ4 gene plays a critical role in the hair cells that translate sounds into nerve signals, and defects in this gene contribute to adult-onset hearing loss." (PMID 37009795, 2023). "Among the 373 families, we detected potential causative KCNQ4 variants in 15 families, indicating that 4.02% (15/373) of the hearing loss cases were potentially caused by KCNQ4." (PMID 37009795, 2023). "The main pathophysiology of hearing loss resulting from KCNQ4 mutation is reduced K+ recycling and continuous depolarization of the OHCs, ultimately leading to OHC death." (PMID 37009795, 2023). "VPA is a candidate drug for inhibiting late-onset progressive hereditary hearing loss from the KCNQ4 p.W276S variant." (PMID 36982769, 2023). "In this study, we identified seven missense KCNQ4 mutations in a cohort of patients with hearing loss." (PMID 37009795, 2023). "Deafness-associated genes KCNQ1 (also associated with heart diseases) and KCNQ4 (only associated with hearing loss) encode the homotetrameric voltage-gated potassium ion channels Kv7.1 and Kv7.4, respectively." (PMID 36140355, 2022). "Variants in KCNQ4, e.g., c.1044_1051del8, Pro291Leu have also been identified that are involved in autosomal recessive and semi-dominant hearing loss, respectively." (PMID 34479475, 2021). "Acoustic noise exposure has been suggested to decrease the functionality of KCNQ4 on the surface membrane, thereby playing a pivotal role in noise-induced hearing loss." (PMID 33801540, 2021). "Our findings were consistent with a previous study which showed that the KCNQ4 gene is likely related to the complex interactions between age, environmental noise, and hearing loss." (PMID 34828318, 2021). "Two SNPs, the rs2070358 G allele in KCNE1 and rs34287852 G allele (c.1365T>G, p.H455Q) in KCNQ4, were reported to be significant in both populations, with the rs2070358 G allele increasing the susceptibility to noise-induced hearing loss." (PMID 33801540, 2021). "Genetic mutations in KCNQ4 are mostly responsible for the nonsyndromic SNHL hearing loss with DFNX (X: X-linked) kinds." (PMID 33367117, 2021). "Two of the affected individuals were homozygous for the variants in genes, GJB2, MPDZ, known to cause recessively inherited hearing loss, while other two affected individuals were heterozygous for a variant in KCNQ4, a dominant deafness-causing genes." (PMID 34946889, 2021). "They found that three SNPs in KCNE1, one SNP in KCNQ1, and one SNP in KCNQ4 were significantly associated with noise-induced hearing loss." (PMID 33801540, 2021). "Understanding of the function, structure, physiology, pharmacology, and genetics of KCNQ4 has indicated that KCNQ4 holds great promise for the discovery and development of drugs useful in genetic, age-related, and noise-induced hearing loss." (PMID 33801540, 2021). "The prevalence of hearing loss, KCNQ4 c.546C>G variant, and hypertension were all significantly higher in the case group." (PMID 34828318, 2021). "KCNQ4 mutations explained 6.62% (19/287) in Japanese families with autosomal dominant nonsyndromic hearing loss and c.211delC was identified as a founder mutation in Japanese individuals, explaining 68.4% (13/19) among families with KCNQ4 mutations." (PMID 33801540, 2021).
hearing loss (continued). "Acousia Therapeutics, which is a biotech company aiming for the development of small-molecule drugs for sensory neuronal hearing loss, has eight compounds targeting KCNQ4 in its pipeline." (PMID 33801540, 2021). "Among the five members of KCNQ family of voltage-gated potassium channels, variants in KCNQ4 are reported to cause autosomal dominant non-syndromic hearing loss in humans." (PMID 34946889, 2021). "Few studies have investigated the association between hearing impairment and the variant c.546C>G of KCNQ4." (PMID 34828318, 2021). "An impaired membrane expression and a disrupted KCNQ4 conductance causes progressive sensorineural hearing loss." (PMID 34408646, 2021). "Mutations in the KCNQ4 gene lead to an autosomal-progressive non-syndromic hearing loss due to the degeneration of the outer and, in a lesser extent, inner hair cells of the cochlea, known as DFNA2." (PMID 34381336, 2021). "In summary, this hospital-based study demonstrated that the c.546C>G variant of the KCNQ4 gene is associated with postlingual hearing loss in an elderly population in Taiwan." (PMID 34828318, 2021). "Most KCNQ4 mutations linked to hearing loss are clustered around the pore region of the protein and lead to loss of KCNQ4-mediated potassium currents." (PMID 31434872, 2019). "In accord with these findings, humans with DFNA2 (a slowly progressing, autosomal dominant form of hearing loss) due to loss‐of‐function mutations in KCNQ4 were better than age‐matched controls at detecting low frequency skin vibration." (PMID 28800673, 2018). "We performed whole-exome sequencing for 98 families with hearing loss and found mutations in KCNQ4 in five families." (PMID 30413759, 2018). "Mutations in potassium voltage-gated channel subfamily Q member 4 (KCNQ4) are etiologically linked to a type of nonsyndromic hearing loss, deafness nonsyndromic autosomal dominant 2 (DFNA2)." (PMID 30413759, 2018). "The present report, which is the first of p.G296D mutation in KCNQ4, adds to our understanding of KCNQ4 mutation-induced hearing loss." (PMID 28340560, 2017). "In the mammalian cochlea, the potassium channel KCNQ4 is highly expressed in outer hair cells and KCNQ4 mutations cause human hereditary hearing loss." (PMID 29093664, 2017). "This suggests that mutation in KCNQ4 can cause autosomal recessive hearing loss with a more severe phenotype than autosomal dominant hearing loss." (PMID 28340560, 2017). "SLC26A4 and CDH23 mutations were frequently identified in patients with severe to profound hearing loss, whereas KCNQ4 gene mutations and m.3243A>G mutations were frequently identified in patients with hearing loss ranging from mild to moderate." (PMID 27627659, 2016). "Salicylate-induced hearing loss is believed to arise from a reduction in the electromotile response of outer hair cells (OHCs) and/or reduction of KCNQ4 potassium currents in OHCs, which decreases the driving force for the transduction current." (PMID 25904892, 2015). "This is the first report of KCNQ4 mutation in Chinese mainland families, providing more information for discovering the molecular mechanism of KCNQ4 mutation-induced hearing loss." (PMID 25116015, 2014). "In this present study, we identified a known mutation and a novel mutation in the P-loop region of the KCNQ4 potassium channel which yielded dominant non-syndromic hearing loss by high-throughput sequencing as well as conventional genetic testing." (PMID 25116015, 2014). "In the case of late onset deafness caused by dominant negative mutations in the gene encoding the potassium ion channel protein KCNQ4 (DFNA2-type monogenic hearing loss), hair cells degenerate apparently due to sustained depolarization." (PMID 22563300, 2012). "To determine how the mutated protein (denoted Tyr270His) induced hearing loss, we built models of the KCNQ4 and Tyr270His pore regions." (PMID 22420747, 2012).
hearing loss (continued). "While conducting an ongoing genetic study of hereditary hearing loss, we identified a mutated KCNQ4 from a Japanese patient in which the encoded Tyr270 residue was replaced with His." (PMID 22420747, 2012). "KCNQ4 gene variants are rare in Cantabria, present in less than 2% of patients with sensorineural hearing loss of unknown origin." (PMID 40178561, 2025). "In KCNQ4, we identified seven missense variants and one deletion variant in 9 hearing loss patients and 14 missense variants in the Korean population with an unknown hearing loss phenotype." (PMID 37009795, 2023). "Interestingly, sequencing also reported missense heterozygous variant (c.778G>C; p.Glu260Gln) of paternal inheritance in KCNQ4 gene, associated with neurosensorial hearing loss." (PMID 37383390, 2023). "To understand the contribution of KCNQ4 variants to hearing loss, we analyzed whole-exome and genome sequencing data from patients with hearing loss and individuals whose hearing phenotypes were unknown." (PMID 37009795, 2023). "Our findings suggest that KCNQ4 variants may be overlooked in hearing loss that starts in adulthood." (PMID 37009795, 2023). "The severity of DFNA2A hearing loss and the rate of progression vary among KCNQ4 variants." (PMID 36140355, 2022). "Finally, we focused on currently developed KCNQ4 activators and their pros and cons, paving the way for the future development of specific KCNQ4 activators as a remedy for hearing loss." (PMID 33801540, 2021). "KCNQ4 has been recognized as one of the most susceptible genes for noise-induced hearing loss." (PMID 34479475, 2021). "In addition, variants of KCNQ4 have also been associated with noise-induced hearing loss and age-related hearing loss." (PMID 33801540, 2021). "An association of KCNQ4 c.546C>G with hearing loss in an elderly population was established." (PMID 34828318, 2021). "Therefore, the discovery of small compounds activating or potentiating KCNQ4 is an important strategy for the curative treatment of hearing loss." (PMID 33801540, 2021). "Researchers led by Heon Yung Gee and Jae Young Choi at Yonsei University College of Medicine, Seoul, South Korea, have now uncovered numerous previously overlooked mutations in the gene encoding KCNQ4 that may also contribute to adult-onset hearing loss." (PMID 31434872, 2019). "To date, 20 mutations in KCNQ4 have been reported to cause hearing loss." (PMID 28340560, 2017). "In past reports, the patients with KCNQ4 mutations showed a similar type of hearing loss." (PMID 27911912, 2016). "For example, dimers of KCNQ3/4 modulate the dynamics of activation of hearing loss-associated candidate KCNQ4 and might contribute to the critical low-voltage activated potassium conductance in both inner and outer hair cells of mice." (PMID 26121033, 2015). "Then we performed mutation screening of KCNQ4 in 71 patients with high frequency hearing loss and 40 unaffected individuals of matched geographical ancestry, and found the deletion of the second intron 47 bp in 5 patients as well as 2 males with normal hearing, the insertion of 47 bp in 11 patients." (PMID 25116015, 2014). "Further functional studies regarding mutations in these residues in KCNQ4 may help clarify the molecular mechanism, which in turn, will facilitate informative genetic counseling, early diagnosis and even treatment of hearing impairment." (PMID 25116015, 2014). "Mutations in KCNQ4 cause an autosomal-dominant type of nonsyndromic hearing loss, DFNA2." (PMID 25140308, 2014). "Despite the significance of the KCNQ4 biogenesis, little is known about the molecular mechanisms that control the process, which hinders the development of strategies to prevent and treat hearing loss of DFNA2 patients." (PMID 23431407, 2013).
hearing loss (continued). "Of the 278 missense KCNQ4 variants in gnomAD, we examined the changing amino acid residues between the transmembrane domains (TM) 5 and 6 (aa 259–296) surrounding the pore region (aa 271–292), as most known KCNQ4 variants linked to hearing loss are clustered around this region." (PMID 31434872, 2019). "Several susceptibility genes for hearing loss are involved in potassium recycling, such as connexin genes (GJB2, GJB3), potassium channels or channel subunits (KCNQ1, KCNQ4) and Na+/2Cl-/K+ cotransporter (SLC12A2)." (PMID 39226169, 2024). "We hypothesized that mutation of Kcnq4 may cause vestibular dysfunction after excessive mechanical stimulation due to the failure of [K+] regulation in the type 1 vestibular hair cell cytosol, similar to the mechanism of noise-induced hearing loss due to Kcnq4 mutation in mouse model." (PMID 38956136, 2024). "Patient YUHL37-21 harboring the p.R331W variant also had moderate hearing loss, whereas Patient YUHL463-21 harboring the KCNQ4 p.R331Q variant exhibited a severe and high-frequency hearing loss pattern." (PMID 37009795, 2023). "The patients harboring KCNQ4 p.R447W and p.G435Afs*61 variants (YUHL206-21 and YUHL261-21) exhibited a flat-type moderate hearing loss pattern." (PMID 37009795, 2023). "Several mutations in the KCNQ4 gene (encoding hKV7.4) have been identified in humans and are often linked to DFNA2 non-syndromic hearing loss, although the possible contribution to pathology remains to be determined for many mutations." (PMID 35642964, 2022). "Interestingly, the rs34287852 G allele in KCNQ4 exhibited the opposite effect in these two populations, as it was found to decrease the risk of developing noise-induced hearing loss in the Swedish population, but increased the susceptibility of noise-induced hearing loss in the Polish population." (PMID 33801540, 2021). "Like DFNA2 (KCNQ4 and GJB3), DFNA5 is also predicted to be a candidate gene for age-related hearing loss (presbyacusis) since DFNA5 variation related hearing loss showed similar phenotypic with presbyacusis." (PMID 29849037, 2018). "KCNQ4 mutations cause deafness nonsyndromic autosomal dominant 2 (DFNA2), which is characterized by progressive sensorineural hearing loss at all frequencies." (PMID 30413759, 2018). "Mutations in KCNQ4 are associated with DFNA2, a nonsyndromic progressive form of sensorineural hearing loss characterized by loss of OHCs." (PMID 29163061, 2017). "Mutations in WFS1, KCNQ4, COCH, and TECTA are frequently detected in individuals with ADNSHL3 and may cause mild to moderate hearing loss." (PMID 30413759, 2018). "In patients with variants in the KCNQ4 gene, additional tests were requested, including a complete blood count, biochemical profile, elemental profile, urinary sediment analysis, and electrocardiogram, to rule out syndromic hearing loss." (PMID 40178561, 2025). "Loss-of-function mutations in the KCNQ4 channel cause DFNA2, a subtype of autosomal dominant non-syndromic deafness that is characterized by progressive sensorineural hearing loss." (PMID 23431407, 2013). "In addition, in our Korean adult-onset hearing loss patient cohort (i.e., Yonsei University Hearing Loss or YUHL cohort) without noise exposure history, KCNQ4 presented the highest prevalence for mutations (9/213 patients, unpublished)." (PMID 33801540, 2021). "Moreover, no pathogenic mutation was found in the ACTG1, KCNQ4, GJB3, or COCH genes in patients with late onset hearing loss and autosomal dominant pedigrees or in patients with sporadic hearing loss." (PMID 30344259, 2018). "In a large genetic study conducted in Taiwan on hereditary hearing loss, researchers initially ruled out variants of the connexin 26 gene and the 1555A > G variant of the MTRNR1 gene, subsequently finding 5 out of 86 cases with pathogenic variants of the KCNQ4 gene." (PMID 40178561, 2025).